INS (insulin)
Diseases named in the same sentence as INS in open-access papers (continued):
Sharing a sentence is not in itself a finding about the gene and the disease.
diabetes (continued). "Our results showed that blackberry juice significantly improved insulin secretion in rats with diabetes, which can result from the effect of therapy on the secretory capacity of β-cells, as well as the improvement of oxidative stress and inflammation in cells of islets." (PMID 37280499, 2023). "Medications for treatment of diabetes whether insulin or oral hypoglycemics are available in all countries." (PMID 37471350, 2023). "Collectively, these data are consistent with protein export defects and suggest that disruptions in Golgi structure may contribute to insulin trafficking defects in diabetes models." (PMID 36997560, 2023). "Insulin-requiring diabetes had a higher risk of MI (1.04%/years) vs both no diabetes (HR 2.58, 95% CI 1.37–4.86, p = 0.003) and non-insulin-requiring diabetes (HR 2.40, 95% CI 1.12–5.12, p = 0.024)." (PMID 35976428, 2023). "The choice of using NPH insulin treatment was based on its widespread use in clinical practice for managing diabetes, and understanding how HBOT affects cardiac function can provide valuable information for developing targeted therapies to mitigate the adverse cardiovascular effects of diabetes." (PMID 37760247, 2023). "The MSigDB Pathways identified as being regulated by the aberrantly expressed mRNAs from the selected matched mRNA–lncRNA pairs include diabetes pathways, metabolism of proteins, glucose regulation of insulin secretion, regulation of insulin secretion, and regulation of gene expression in β cells." (PMID 38027148, 2023). "In addition, it also lowered fasting insulin levels, increased insulin sensitivity in people with pre-diabetes and obesity, improved glucose tolerance, and reduced serum glucose excursions." (PMID 37630716, 2023). "Further studies show that patients with diabetes who require insulin or oral hypoglycemic drugs have an increased chance of LOS > 4 days and higher rates of postoperative complications compared with non-diabetic patients, and our findings are consistent with these results." (PMID 37430329, 2023). "Historically, “DM on insulin” has been used in RCRI as an arbitrary marker of severity of diabetes." (PMID 37035307, 2023). "The present algorithm may help to select the best CGM device based on patients’ clinical characteristics, needs and clinical context, offering a further opportunity of a “tailored” therapy for people with insulin-treated diabetes." (PMID 37676398, 2023). "Diabetes duration in insulin groups was significantly higher than oral group." (PMID 37828117, 2023). "The proportion of participants with either diabetes or hypertension, or taking insulin, antihypertensive or cholesterol-lowering medication was higher relative to individuals with suspected AMD or glaucoma, but lower in comparison to those with retinopathy with microaneurysms." (PMID 36329166, 2023). "Similarly, people with type 2 diabetes mellitus (T2DM) have abnormal secretion as well as the action of insulin." (PMID 37109046, 2023). "They classified patients type of diabetes clinically; those who were diagnosed in childhood, with a lower BMI and requiring immediate insulin treatment were classified as T1DM whereas patients who were diagnosed with diabetes aged >30 years/old and with metabolic features were classified as T2DM." (PMID 38370534, 2023). "However, treatment with WJMSC-CM (P < 0.0001) or insulin (P < 0.001) significantly increased oligodendrocyte numbers compared to the untreated diabetes group." (PMID 37081849, 2023). "In the context of HFrEF, the use of insulin to treat diabetes is associated with a higher risk of adverse outcomes, regardless of the greater severity of diabetes." (PMID 37542280, 2023). "This will be done through a dashboard that will contain diabetes care plans (eg, recommendations of insulin doses), real-time data from connected devices, educational resources, and assigned tasks (eg, completion of blood work) to enhance personalization of pediatric diabetes care." (PMID 37440296, 2023).
diabetes (continued). "Additionally, we found that almost half of patients with diabetes were discharged with insulin therapy, whereas there was a significant reduction in the prescription of noninsulin therapies at discharge as compared with the admission." (PMID 36964858, 2023). "Besides the role in the modulation of insulin signaling, there are studies referring to the regulating effects of Sestrin2 on peripheral tissues which play key roles in the pathogenesis of diabetes, such as adipose tissues and skeletal muscle." (PMID 37920252, 2023). "Relative to women without diabetes, neither baseline metformin nor insulin use among women with T2D was associated with BCa risk." (PMID 37402868, 2023). "Recent studies have evaluated the clinical effectiveness of the MiniMed 780G AHCL system in patients previously using advanced diabetes technologies, including continuous subcutaneous insulin infusion (CSII) or the CGMS or both combined to some degree in automated technologies." (PMID 36692945, 2023). "The mean duration of diabetes was 9.7 (SD 6.0) years, and 35.8% received insulin treatment." (PMID 37328848, 2023). "While not all diabetics are subscribed to the NDSS, given the incentives they provide to people with diabetes, including subsidised glucose monitoring products, insulin pen needles and pump consumables, it is assumed that it captures almost all Australian patients." (PMID 36334194, 2023). "In the last few years, with the advent of the application of NGS sequencing for genetic diagnosis of monogenic diabetes, further cases of MODY caused by defects in different genes involved in insulin release in response to blood glucose levels have been described." (PMID 37240725, 2023). "The peroxisome proliferator-activated receptor (PPAR) has three isotypes, α, δ, and γ, and is a nuclear receptor superfamily that may have an impact on insulin sensitivity, inflammation, lipid metabolism, and insulin secretion in the treatment of diabetes." (PMID 37894680, 2023). "DPP4 inhibitors like APL and PVI are potential antidiabetic peptides for lowering glycemic indices, lowering the amount of glucagon, and maintaining insulin levels in type 2 diabetes mellitus, and their activities are indirectly facilitated by the continuous presence of GLP-1 incretin." (PMID 36982902, 2023). "Insulin secretion from pancreatic β-cells plays an important role in glucose homeostasis, and dysregulation of this process is directly involved in the etiology of diabetes." (PMID 38124716, 2023). "If someone has type 1 diabetes mellitus, for example, they really ‘must’ take insulin if they have any regard for their life or health, and it is necessary for a professional to emphasize that failure to take insulin will inevitably lead to death." (PMID 36750907, 2023). "Interestingly, in the sub-analysis of the ARISTOTLE trial based on the diabetes status, only insulin-treated diabetes was a predictor of future MIs (HR 2.34) compared with no diabetes." (PMID 35976428, 2023). "In addition, further developments, including self-monitoring devices, intravenous insulin, glucagon, insulin pumps, and better and automated glucose meters, have revolutionized the treatment of diabetes, improving patient outcomes." (PMID 37036866, 2023). "Currently, insulin injections are still the first-line treatment for diabetes." (PMID 37514488, 2023). "When low doses of streptozotocin were administered to SGLT2−/− and Sweet Pee mice to create a diabetes model via impaired insulin secretion, hyperglycemia was improved in both cases, but mortality was reported to be increased in Sweet Pee compared to wild-type mice." (PMID 37047250, 2023). "There is solid evidence presenting the link between type 2 diabetes and low blood testosterone levels due to an amplified insulin signaling pathway, as evidenced by multiple studies showing a high incidence (30–80%) of hypogonadism in males with diabetes mellitus." (PMID 36961066, 2023).
diabetes (continued). "Further, there are numerous reports showing that regular exercise in patients with diabetes improves insulin sensitivity, reduces glycosylated hemoglobin (A1C), and decreases fasting insulin levels as well as fasting blood sugar, especially when physical activity is combined with healthy diet." (PMID 36834808, 2023). "Diabetes mellitus (DM) is a chronic disease characterized by a disorder in carbohydrate, fat and protein metabolism that occurs as a result of hyperglycemia due to insufficient insulin hormone." (PMID 38813509, 2023). "In some circumstances, insulin therapy may fail to control the evolution of diabetes and its consequences in some circumstances." (PMID 37375806, 2023). "Lactobacillus was significantly decreased following the progression from healthy to prediabetic phenotype and further decreased following diabetes development and was negatively correlated with fed and fasting glucose and positively correlated with fed insulin." (PMID 37233701, 2023). "Recent studies have identified low fasting insulin levels as an independent predictor of all-cause mortality and cardiovascular mortality in patients with acute decompensated heart failure without diabetes mellitus." (PMID 38505536, 2023). "In the current study, the relationship between BMI-SDS increase and both diabetes duration and the amount of insulin used was stronger in the female sex, possibly suggesting that female children with type 1 diabetes are at higher risk of weight gain during puberty." (PMID 36700969, 2023). "Finally, it is important to note that people with diabetes have a wide range of insulin requirements, bolus patterns, dietary habits, exercise habits, and many other lifestyle considerations that affect glycemic control." (PMID 37751154, 2023). "Contrarily, genetic variations affecting insulin secretion and resistance impact diabetes." (PMID 37868449, 2023). "Diabetes mellitus (DM) is a chronic metabolic disease characterized by abnormal insulin‐dependent glucose metabolism, which disrupts the homeostasis of bone minerals, such as calcium, phosphorus and magnesium, leading to diminished bone mass and structural deterioration." (PMID 37621124, 2023). "Preparations of insulin and its analogues, entering the body, in addition to the direct therapeutic effect in the treatment of diabetes mellitus, can provoke undesirable effects, which are known as insulin amyloidosis and toxic effects on cells at injection sites." (PMID 36835194, 2023). "One in three Medicare beneficiaries has diabetes, and 3.1 million Part D enrollees require insulin." (PMID 36751859, 2023). "Diabetes mellitus is a group of metabolic disorders with different etiologies, pathogeneses and clinical pictures, characterized by chronic hyperglycemia due to abnormal insulin secretion or action." (PMID 36768715, 2023). "Similarly, in type 1 diabetes mellitus, autoantibodies to insulin that has undergone oxidative post-translational modification are significantly more common than those to native insulin." (PMID 37334358, 2023). "Additionally, insulin exerts little impact on cardiovascular complications, a key contributor to morbidity and mortality in patients with diabetes." (PMID 37621313, 2023). "Furthermore, the secretion of adipokines from visceral fat, abundant in morbidly obese individuals, can lead to systemic inflammation and impaired insulin signaling, setting the stage for the onset of type 2 diabetes mellitus." (PMID 37892574, 2023). "Accordingly, the factors including PE and EE were identified to be high among the participants reflecting the improved performance and reduced efforts in managing diabetes, which may lead to improved BIs in the adoption of insulin biosensors." (PMID 38239544, 2023).
diabetes (continued). "This initial characterization of resistin led to the hypothesis that it might serve as a pivotal link between obesity and diabetes, largely based on preliminary evidence suggesting that resistin can inhibit insulin activity in rodent models." (PMID 37761031, 2023). "Clinical recommendations include being alert to the possibility of this behaviour in males with Type 1 Diabetes Mellitus and the need for health professionals to use open-ended questions to explore current and past deliberate restriction and/or omission of insulin among their patients." (PMID 37255778, 2023). "We aimed to assess whether BMI, residual beta cell function measured by plasma “C” peptide and insulin resistance measured by eGDR have any impact on the development of DD and microvascular complications in patients with type 1 diabetes mellitus (T1DM)." (PMID 38111445, 2023). "Our finding regarding the ability of the biliary tract epithelium to produce extrapancreatic glucagon and insulin may contribute to improving the treatment of diabetes." (PMID 38094502, 2023). "Diabetes mellitus (DM) is a chronic metabolic disorder characterized by high blood sugar levels and impaired metabolism of carbohydrates, lipids, and proteins due to insufficient insulin secretion and/or insulin action." (PMID 37332421, 2023). "They had preserved insulin secretory function or newly diagnosed diabetes at pre-transplant." (PMID 37424863, 2023). "Furthermore, Gls2 CKO exhibited significant diabetes mellitus with gluconeogenesis and insulin resistance when fed a high-fat diet." (PMID 37147373, 2023). "Studies conducted in people with pre-diabetes, hypertension and MS indicate a beneficial effect of eTRF on metabolic parameters (fasting glucose, fasting insulin, lipid profile, oxidative stress, hypertension, postprandial insulin), even without total body fat mass reduction." (PMID 36986052, 2023). "T. gondii appeared to be interrelated to diabetes mellitus (DM) as it had been considered an inducer of Type I DM by damaging the pancreatic β cells to prohibit insulin production; besides, its role in Type 2 DM by inducing chronic low-grade inflammatory reactions." (PMID 37719029, 2023). "Our study links ENPL-1 and ASNA-1, and provides information on how they might cooperate to produce insulin maturation and secretion, and prevent diabetes." (PMID 36939052, 2023). "In iIGT, peripheral resistance (muscle and fat) and relative insulin secretion impairment seem to play an essential role in developing pre-diabetes and diabetes, while in the case of iIFG, insulin resistance and hepatic glucose production have the primary role." (PMID 36788521, 2023). "Diabetes is a wide group of metabolic diseases of different pathogeneses, etiologies and clinical pictures, characterized by chronic hyperglycemia as a result of incorrect insulin action." (PMID 36768715, 2023). "However, we excluded patients taking continuous insulin therapy within 3 months of diabetes diagnosis to exclude possible type 1 diabetes." (PMID 38032635, 2023). "It should be noted that a few features of diabetes may contribute to the severity of stigma, e.g., insulin injection, blood sugar control, nutritional restrictions, obesity, and hypoglycemia." (PMID 37570425, 2023). "Diabetes is a metabolic disease caused by low insulin production or insulin hormone not functioning properly, or it is caused by both." (PMID 36679105, 2023). "Gradually, glucose intolerance and then diabetes mellitus develop as a result of decreased insulin production and deteriorating beta cell activity.Age is one factor that affects insulin sensitivity, and several researchers have found that there is a progressive increase in IR as age increases." (PMID 37814679, 2023). "However, the accuracy of CBGM needs to be improved to allow all patients with diabetes to administer insulin accurately and prevent hyperglycemia and hypoglycemia." (PMID 37568877, 2023).
diabetes (continued). "Thus, the insulin secretion process is considered as a promising target for the treatment of diabetes mellitus." (PMID 37601108, 2023). "When performing a subanalysis of the TPIAT group based upon insulin use at 24 months, ongoing insulin dependence (n = 11) resulted in a significantly lower (worse) diabetes symptom summary score (p=0.03) than was found in the insulin-independent cohort (n = 5)." (PMID 40303247, 2023). "If feelings of frustration with diabetes management can lead to restriction of food or insulin, then screening for DD could uncover distress before patients begin to act on it." (PMID 38041170, 2023). "This may have implications for development of both diabetes and cardiovascular disease due to improved insulin sensitivity." (PMID 36305961, 2023). "Moreover, administering Bifidobacterium bifidum (1 × 107–2 × 109 CFU/mL) reduced fasting blood glucose, insulin resistance, and improved sensitivity in human participants with diabetes and animal models." (PMID 37175825, 2023). "Moreover, the use of CGM at the onset of diabetes allows patients to be aware of the glycemic trends and their changes following insulin therapy." (PMID 37676398, 2023). "Overall, the A7+TouchCare may be a valuable alternative to Omnipod or other insulin patch pumps in some patients with diabetes." (PMID 37616289, 2023). "ER stress signaling is closely related to various pathological factors and states of cognitive decline in diabetes, such as metabolic abnormalities, cerebral ischemia, insulin resistance, neuronal calcium homeostasis, neurotransmitter changes, inflammatory response, and oxidative stress." (PMID 38127000, 2023). "However, the study results still do not support the recommendation to use this modality as a substitute for insulin in critically ill patients with type-2 diabetes mellitus and COVID-19, especially if therapy must be started in severe conditions." (PMID 37168726, 2023). "Several variables, such as duration of diabetes, HbA1C level, and type of antidiabetic medications (oral pills or Insulin), were unavailable in the dataset we used to consider in the analysis, which may affect the study results." (PMID 36899306, 2023). "On the basis of results obtained from our study, it can be concluded that increased FGF21 concentration observed in diabetes may result from a compensatory reaction to impaired insulin sensitivity or tissue resistance to this cytokine." (PMID 37869250, 2023). "The insulin OOP payment among insured individuals with diabetes was stable." (PMID 36751859, 2023). "The results of in vivo experiments in diabetic rats showed that only one insertion of the MN patch could achieve sustained release of insulin within 1 d, which had a prominent therapeutic effect on diabetes." (PMID 37223469, 2023). "Therefore, we propose the possibility that the relationship between Cre/BW ratio and progression from pre-diabetes to diabetes is mediated through insulin resistance." (PMID 38044422, 2023). "A recent study has shown a strong association of serum complement C3 with serum insulin and insulin resistance in subjects with PCOS, suggesting that this inflammatory marker might predict future diabetes and CVD complication risk in subjects with PCOS." (PMID 36980195, 2023). "There were people with diabetes who suffered severe complications (eg, diabetic ketoacidosis and end‐stage renal disease) and died owing to insulin rationing with the poor affordability of insulin." (PMID 36751859, 2023). "Both negative affect generally and negative diabetes-related affect have previously been associated with increased odds of restricting insulin." (PMID 37255778, 2023). "In view of the complexities in the care of those with insulin-treated T2DM, the aims of this study were to compare the local achievement of metabolic targets, diabetes management, and associated risks between renal patients with insulin- and noninsulin-treated T2DM." (PMID 37152098, 2023).